RNU6-245P (RNA, U6 small nuclear 245, pseudogene)
Gene: Small nuclear RNA gene on chromosome X (68,539,443 to 68,539,549, reverse strand). Ensembl gene ENSG00000206747.
Homologues: Orthologues: chimpanzee U6 (100% identical), macaque U6 (93% identical), rabbit U6 (69% identical). Paralogues in human: RNU6-21P (85% identical), RNU6-1024P (84% identical), RNU6-1145P (84% identical), RNU6-15P (84% identical), RNU6-38P (84% identical), RNU6-1 (83% identical), RNU6-16P (83% identical), RNU6-2 (83% identical), RNU6-39P (83% identical), RNU6-3P (83% identical), RNU6-480P (83% identical), RNU6-4P (83% identical), and 1288 more.